CD40 (CD40 molecule)
Diseases named in the same sentence as CD40 in open-access papers (continued):
Sharing a sentence is not in itself a finding about the gene and the disease.
cancer (continued). "In contrast, in the setting of cancer, a recent study has developed a bispecific FAP-CD40 antibody, to induce CD40 stimulation solely in the presence of a fibroblast activation protein (FAP), to induce antitumor immunity." (PMID 39321281, 2024). "In mouse models of cancer, TAM activation using Toll-like receptor (TLR) activators and CD40 agonist have been explored." (PMID 38543739, 2024). "mAbs targeting CTLA4, PDCD1, CD274, and LAG3 have been approved by the FDA for second- and first-line treatment against cancer, whereas mAbs targeting ICOS and CD40 are under investigation." (PMID 37215135, 2023). "Amongst the clearest examples of bell-shaped dose response effects in humans treated with TNF receptor agonist antibodies include data from cancer patients treated with BMS-986178 (anti-OX40 mAb), PF-04518600 (anti-OX40 mAb) or mitazalimab (anti-CD40 mAb)." (PMID 37795079, 2023). "Next, we explored macrophage and cancer cell viability following CSF1/CSF1R pathway inhibition and CD40L/CD40 pathway activation in the MTS for 4 and 7 days." (PMID 37346794, 2023). "The immunosuppressive phenotype CD8+PD‐1+ was avoided in the cancer cells (PanCK+) neighborhood (black circle; row 15, column 21) in NDES CD40 and IP CD40 compared to UnTx." (PMID 36658712, 2023). "Due to the importance of the CD40/CD40L axis in antigen-specific immune responses especially, cancer therapeutics involving CD40 have been and continue to be explored." (PMID 36894898, 2023). "NKT cells activate the DC cells by affecting α-GalCer, strengthening the immune system response against cancer cells, and mediating the interactions between TCR and CD1d, as well as CD40L and CD40." (PMID 37158883, 2023). "A number of inhibitory immunoreceptors have been identified and studied in cancer in past decades, including but not limited to PD-1, PD-L1, CTLA-4, LAG3, HAVCR2, TIGIT, CD69 and CD40." (PMID 37989761, 2023). "Yet, agonistic anti-CD40 (αCD40) monoclonal antibodies mimic CD40L in vivo and have been shown to enhance the immunogenicity of cancer vaccines and trigger cancer regressions, including in pancreatic cancer." (PMID 37444617, 2023). "In the present study, SRSF9 expression had been shown to positively correlate with most of the 47 immune checkpoint genes in most cancers, such as CD276, CD86, CTLA-4, and CD40." (PMID 35069733, 2022). "From these, CD40 and DEC-205 have been the most widely used for cancer and infectious diseases and moved into clinical development." (PMID 36016929, 2022). "Given the multiple ongoing trials, using agonistic mAbs, such as CD40 and TLR agonists, to promote cancer-cell killing by immune cells holds much promise." (PMID 36211808, 2022). "Co-stimulatory molecules, including CD40, OX40, and 4-1BB antibodies, have been used in combination with cancer vaccines to augment cancer vaccine efficacy by increasing immunogenicity." (PMID 36613591, 2022). "We found that plasma levels of EVs expressing PD-L1, CD40, CD40L or TNF-RII were significantly reduced after cancer treatment." (PMID 35655072, 2022). "The present analysis found elevated expression of CD47 not only positively correlated with PD1, PD-L1, CTLA4, but also with multiple other immune checkpoints such as IDO1, CD40, CD160, CD86, CD44 across various cancer types." (PMID 35697717, 2022). "As previously reported, in the cancer-immunity cycle, CD28: (CD80, CD86), CD40, CD27, HVEM, GITR: GITRL, ICOS, and TLR-2 are stimulatory factors, while TIM-3, PD-L1: PD-1, PD-L1: (CD80, CD86), CTLA-4: (CD80, CD86), BTLA, and LAG-3 are inhibitory factors." (PMID 35419462, 2022). "This phenotype of metastatic LN T cells is preceded by the suppression of LN-resident DCs, which are less mature and express decreased levels of the activation markers CD40, CD86 and CD83 than healthy and cancer-free LN DCs." (PMID 36139665, 2022). "CD40 is a TNF family member expressed on antigen-presenting cells (APCs) like dendritic cells, macrophages, and B cells and some cancer cells." (PMID 34765538, 2021).
cancer (continued). "CD40 is a member of the tumor necrosis factor (TNF) family and is a new immune‐modulating target with great potential in cancer treatment." (PMID 34184409, 2021). "Currently, a variety of CD40-targeting agonist monoclonal antibodies are in phase 1 in clinical trials, including CDX-1140 and CDX-301 for the treatment of advanced malignant tumors and solid tumors." (PMID 34683963, 2021). "In the TME, the surface of M1 macrophages is rich in TLR2/TLR4, CD80, CD86, CD40, CSF1, IL-1R1, INF-γ-R and MHC-II receptors, which are often used as targets for cancer therapy." (PMID 34683963, 2021). "A number of T cell costimulatory molecules including CD137, OX40, CD40, ICOS, GITR, and CD27 are being targeted pharmacologically with agonists to improve outcomes in cancer patients." (PMID 34290245, 2021). "Agonistic CD40 monoclonal antibodies (αCD40) mimic CD40L in vivo and have been shown to enhance the immunogenicity of cancer vaccines and trigger the regression of highly immunogenic tumors." (PMID 34167573, 2021). "Since CD40 signaling is activated in lymph nodes from CLL patients and in tonsils of non-cancer patients, we performed ISH analysis in five lymph nodes from five CLL patients (LN1-LN5) and in two tonsils from two non-cancer patients." (PMID 33445508, 2021). "CD40 has a dual function in cancer promotion and immune system activation such as APC, T-lymphocytes, and macrophages to kill cancer cells." (PMID 34679012, 2021). "There are several other examples for the ectopic expression of immune cell genes in cancer, such as CD36, CD70, CD40, CD47, CD172 and IDO1." (PMID 34885093, 2021). "The modulation of members of the tumor necrosis factor receptor family (TNFR) including CD40, OX40, and 4-1BB is also currently a focus of investigation, with amplification of CD27 signaling being explored for cancer immunotherapy." (PMID 32665635, 2020). "Today, more than 20 clinical trials using CD40 agonists like APX005M, Selicrelumab and CDX‐1140 are ongoing in cancer of which at least four are also including PDAC (NCT03214250, NCT02376699, NCT03329950 and NCT03193190)." (PMID 32821382, 2020). "The data we presented here support a future clinical trial of IL‐15 combined with a CD40 agonist for PDAC, since we showed for the first time that this combination holds great potential for improved cancer treatment outcome." (PMID 32821382, 2020). "The concept of non-death domain TNF super family receptors (TNFSFR) involved in cell death has been previously reported in cancer cell lines for FN14, CD40, TNFR2, and CD30, acting through a TNF/TNFR1 axis." (PMID 31541082, 2019). "Immunogenicity in vitro was analyzed by co-culturing of dying cancer cells with bone-marrow derived dendritic cells (BMDCs) and rate of phagocytosis and maturation (CD11c+CD86+, CD11c+CD40+) of BMDCs and production of IL-6 in the supernatant were measured." (PMID 31842994, 2019). "Of note, HDACIs have been demonstrated to exert immunomodulatory effects in cancer cells, such as enhanced expression of natural killer cell–activating ligands, MHC class I and II molecules, and CD40 molecules." (PMID 28915584, 2017). "Three genes, CD40, OAS2, and CXCR1, were identified as potential biomarkers of normal tissue toxicity in cancer patients after radiotherapy." (PMID 28443095, 2017). "The precise role of CD40 in this context is controversial, as ligation of CD40 has been shown to inhibit growth of HNSCC cell lines while also inhibiting cancer cell apoptosis and increasing secretion of proangiogenic cytokines." (PMID 31093342, 2016). "Much research has been carried out on CD40 signalling and its ability to induce either pro-survival or pro-apoptotic signals depending on the way the CD40L engages with its receptor in carcinomas." (PMID 26986513, 2016). "Clinical targeting of TNFR family of receptors (CD40, CD134 and CD137) with immunostimulatory monoclonal antibodies has been successful in cancer immunotherapy." (PMID 26500773, 2015).
cancer (continued). "In conclusion, we demonstrate that CD40 expression upregulates the chemokine receptor CXCR5 and promotes MDSC migration toward and accumulation within cancer." (PMID 26462153, 2015). "Therefore, targeting CD40 or CXCR5-CXCL13 signaling may provide a novel cancer therapy strategy." (PMID 26462153, 2015). "Particularly, many cancer-related genes including CDH5, BVES, CX3CL1, FGFR1, IGF1 and CD40 were identified in SIN_D." (PMID 25774687, 2015). "Thus, anti-CD40 mAbs may help mediate cancer cell killing by effector cells." (PMID 25324844, 2014). "Studies on the stimulation of CD40 present on cancer cell lines in the bladder, pancreas, or breast through the recombinant CD40L have shown increased expression of ICAM and Fas by cancer cells and the production of IL-6, IL-8, GROα, GM-CSF, and TNF-α." (PMID 25117071, 2014). "Their findings indicate that permanent activation of CD40 by CD40L inhibits proliferation and enhances apoptosis of cancer cells." (PMID 25117071, 2014). "Various co-stimulatory TNFL/TNFR pairs, including CD40L/CD40, CD70/CD27, 4-1BBL/4-1BB, and OX40L/OX40, have gained prominence as possible targets for cancer immunotherapy, in particular with the aim of induction or (re)activation of antitumor T-cell immunity." (PMID 23840967, 2013). "The induction of high levels of CD40 on DC matured with IRX-2 indicates that these cells are unlikely to induce tolerance, a clearly undesirable event in cancer patients receiving immunotherapy." (PMID 23408925, 2013). "In the section next I will discuss the biology of CD40L/CD40, CD70/CD27, 4-1BBL/4-1BB and OX40L/OX40 and highlight their current status for cancer immunotherapy." (PMID 23840967, 2013). "As for the use of OK432 in cancer immunotherapy, we have demonstrated that OK432 is better than the cytokine cocktail in several critical aspects, i.e. IL-12p70 and IL-15 production, CD40 expression and T-cell stimulation." (PMID 21208424, 2011). "Binding of CD40 to its ligand, CD40L, promotes maturation and activation of immune cells and enhances cytokine production, which modulates immune responses, and in turn induces cancer cells to undergo extensive apoptosis while preserving normal cells." (PMID 39958359, 2025). "To first evaluate the role of CD40 expressed by host cells, we challenged mice lacking CD40 or CD40L with TAg+ cancer cells." (PMID 40397730, 2025). "Furthermore, co-culturing immature dendritic cells with dying cancer cells targeted by EGFR and TF NIR-PIT agents mediated enhanced dendritic cell maturation, as indicated by increased expression of CD80, CD86, CD40, and HLADR." (PMID 41362788, 2025). "The outcome of CD40 signaling is subject to variation, influenced by the nature of CD40L (whether soluble or membrane-bound), signal intensity, specific cancer cell pathway modifications, and, now, also the cellular origin of CD40L." (PMID 40397730, 2025). "Unlike its supportive role in immune activation, CD40 signaling can trigger cell death in cancer cells, likely because of changes in cellular redox levels that occur with the malignant transformation of these cells." (PMID 40397730, 2025). "Similarly, autologous whole cancer cell vaccines composed of irradiated cancer cells pulsed with TLR agonists and anti-CD40 were shown to induce a strong anticancer immunity and prolonged survival of tumor-bearing mice in a way dependent on T cells." (PMID 39301248, 2024). "Moreover, a substantial enrichment of CD4+, CD4+PD‐1+, and Foxp3+ phenotypes cell populations near cancer cells were observed in UnTx compared to IP CD40 and NDES CD40 (dotted black rectangle; rows 11, 12, and 13, respectively, and column 21)." (PMID 36658712, 2023). "The CD40/CD40L costimulatory pathway is an important checkpoint in both IMRDs and cancer." (PMID 37435963, 2023). "The CD40 signaling axis is well characterized and here we compare next generation HERA-Ligands to conventional monoclonal antibody based immune modulation for the treatment of cancer." (PMID 37304285, 2023).
cancer (continued). "CD40, a member of the tumor necrosis factor receptor (TNFR) family, is known to be involved in immune system regulation, acting as a costimulatory molecule, and in antitumor responses against cancer cells." (PMID 37970926, 2023). "Thus, six major ICs for cancer immunotherapy were analyzed in this work, namely CTLA4, PDCD1, CD274, ICOS, LAG3, and CD40." (PMID 37215135, 2023). "Upregulated FasL induced by Fas-CD40 stimulation could also enhance CAR-independent cancer cytotoxicity, especially with heterogeneous cancers." (PMID 37200859, 2023). "In contrast, when dendritic cells are co-incubated with ferroptotic cancer cells at the intermediate and late stage, they mature to a much greater extent as revealed by increased expression levels of CD86, CD40, and MHCIIhigh, while the expression of PD-L1 decreased." (PMID 35760796, 2022). "The immunosuppression effects brought by the blockade of CD40/CD40L might make patients exposed to high risks of severe infection and cancers." (PMID 36437950, 2022). "Our findings reveal a clinically feasible approach to mitigate toxicity without impairing efficacy in the use of agonist CD40 antibodies for cancer immunotherapy." (PMID 34101617, 2021). "The main HSP-activated receptors involved in cancer progression are Low density lipoprotein receptor-related protein 1 (LRP1), Toll Like Receptors (TLRs), the EGF receptor family (ERBB) and cluster of differentiation 40 (CD40)." (PMID 33544155, 2021). "It is well known that the costimulatory protein CD40 and CD80 molecules, which bind to helper T cell ligands, are generally expressed on B cells, macrophages, and dendritic cells, but only rarely expressed on cancer cells." (PMID 32325684, 2020). "CD40 is a member of the Tumor necrosis factor (TNF) receptor family and is expressed by a range of different cell types including DCs, B cells, platelets and non-hematopoietic cells such as endothelial cells, fibroblasts and some types of cancer cells." (PMID 33101304, 2020). "Second, independent of the need for expression of CD40 on cancer cells, agonistic anti-CD40 can be potent stimulants of the immune system, with significant potential synergy in combination with other treatments." (PMID 32331490, 2020). "CD40 is present on multiple cell types including DCs, macrophages, T cells, and B cells, non-immune cells, but also some cancer cell types, where CD40 ligation led to growth inhibition." (PMID 32674488, 2020). "mDCs manufactured using GM-CSF and IL-4 primed with OK-432 for clinical use expressed the HLA−ABC+DR+CD40+CD80+CD86+CD197+ phenotype, harboring bioactive functions that could be useful in providing personalized vaccines for cancer immunotherapy." (PMID 31546936, 2019). "Of these, the average expression of the two genes, including CD70 and PDCD1, and the 12 isoforms derived from the seven genes, including CD40, CD70, IL6, IL10, STAT1, STAT6, and TNFRSF14, were cancer immunotherapy-related genes (false discovery rate (FDR) < 0.01)." (PMID 31292525, 2019). "ICOS has similar functions to CD28 in its control of T cell proliferation and IL-10 production, but additionally it controls CD40/CD40L dependent antibody class-switching and therefore immunological memory, properties which are desirable for anti-cancer vaccination." (PMID 30788290, 2019). "Furthermore, we propose the CD40:CD40L immune checkpoint as a therapeutic target for metabolic disease, CVD, and cancer." (PMID 28738836, 2017).
cancer (continued). "Previously, our lab described the development of a synthetic ligand-inducible MyD88/CD40 (“MC”) fusion protein, comprising signaling elements from MyD88 and CD40, two FKBP12-based ligand-binding domains, and a myristoylation membrane localization domain, as an adjuvant for cancer vaccines." (PMID 27741278, 2016). "Taken together, these results suggest that NORE1A expression is driven by membrane-bound but not sCD40L in CD40-positive carcinomas." (PMID 26986513, 2016). "The precise form of the CD40 stimulus affects these responses with the most profound effects in carcinoma cells being induced by membrane-bound (mCD40L) rather than recombinant soluble CD40L (rsCD40L)." (PMID 20211016, 2010). "Moreover, in mice, positive effects of dual CD40 and TLR activation have been well-described, providing further pre-clinical rationale to test CD40/TLR9 combined therapy in human cancer patients." (PMID 19906293, 2009). "Despite these landmark studies, the clinical translational of CD40 activation in cancer patients has been limited, owing primarily to the lack of an appropriate and available drug." (PMID 19906293, 2009). "Conversely, all but one mouse in the E8I-Cre × CD40Lfl/fl group developed tumors, regardless of whether the cancer cells expressed CD40." (PMID 40397730, 2025). "CD40L expressed by CD8+ T cells may either engage in the traditional cross-talk with host CD40+ antigen-presenting cells to enhance antitumor immunity or induce CD40-dependent noncanonical cytotoxicity in CD40+ cancer cells." (PMID 40397730, 2025). "In untreated cultures, CD40 expression on TAg+ cancer cells was almost absent but increased following incubation with transforming growth factor–β (TGFβ), a cytokine that is frequently found in tumors and observed to be elevated in LoxPTAg mice that developed tumors." (PMID 40397730, 2025). "Thus, our analysis reveals that tumors infiltrated with higher frequencies of CD40L-expressing CD8+ T cells are better positioned to leverage the cancer’s vulnerability to CD40-mediated noncanonical cytotoxicity." (PMID 40397730, 2025). "In cancer, the corresponding signal transduction after PRR stimulation amplifies the effect of the immunosuppressive response of MDSCs by producing a variety of proteins, including arginase-1, iNOS, IDO-1, prostaglandin E2, PD-L1, CD40, TNF-α, IL-1β, IL-6, cyclooxygenase-2, and others." (PMID 39035356, 2024). "This targeting mechanism of ExoDS may be attributed to a variety of membrane receptors like integrin α and β chains (αMβ2), ICAM-1, MFG-E8, TNF, FasL, CD86, CD80, CD40, CD83, MHC-I, MHC-II, NKG2D, IL-15Rα, CD21, CD11c, and CCR7, which help mDC-derived exosomes identify cancer cells." (PMID 38903193, 2024). "In addition to hematopoietic cells, CD40 is expressed on non-hematopoietic cells, including epithelial cells, endothelial cells and even cancer cells." (PMID 37304285, 2023). "However, it should be emphasized that the use of monotherapy with an anti-CD40 agonist resulted in no, or minimal clinical response in cancer patients; as such, it can be concluded that therapy with CD40 agonists should only be used in combination." (PMID 36980527, 2023). "The CAFDL signature was significantly positively associated with TGFB1, CD276, CD40, VEGFA, VEGFB, etc., but showed significantly negative correlation with immune checkpoints (such as CD274, PDCD1, CTLA4, TIGHT, and HAVCR2) and anti-cancer immune regulators (IFNG, IDO1, and GZMA)." (PMID 35967425, 2022). "While the efficacy of CD40-based cancer vaccines in preclinical models is clear, aside from the dependence on T cells, primarily but not absolutely CD8+ T cells, the mechanism of action of effective therapeutic CD40-based cancer vaccines is still under investigation." (PMID 34282297, 2022).